CDH1 (cadherin 1)
Diseases named in the same sentence as CDH1 in open-access papers (continued):
Sharing a sentence is not in itself a finding about the gene and the disease.
colon carcinoma (continued). "A previous study demonstrated that by removing dimethylation of lysine 4 on histone H3 (H3K4m2) at the CDH-1 promoter, LSD1 downregulates the CDH-1 expression, and consequently promotes metastasis of colon cancer cells." (PMID 28779166, 2017). "In lung and colon cancer, Jarid2 is involved in EMT process induced by TGF-β through EZH2-mediated transcriptional repression of CDH1 and microRNA-200 family genes." (PMID 28445934, 2017). "Furthermore, western blot experiments also showed that SERPINC1 regulates the migratory capacity of colon cancer cells by regulating the expression of VIM and Cdh1 in colon cancer cells." (PMID 38923313, 2024). "Collectively, these results indicate that the combination between the two antagonist genes (CDH1 and VIM) could represent a valuable prognostic marker in colon cancer." (PMID 29352232, 2018). "In colon cancer cells, TGIF2 directly interacts with PKM2 in the nucleus by EMT stimulation, and recruits histone deacetylase 3 to the CDH1 (E-cadherin) promoter sequence, which subsequently deacetylates histone H3 and suppresses CDH1 transcription." (PMID 30333907, 2018). "In this study, we assessed these possible LSD1-targets, including CABYR and CDH1, which could be the newly identified target genes by comparing the effects of LSD1 in the two colon cancer cells." (PMID 28121627, 2017). "Our previous studies indicated that LSD1 may facilitate the metastasis of colon cancer by decreasing the dimethylation level of H3K4 at the CDH1 promoter and by repressing E-cadherin transcription, which was consistent with the present results." (PMID 28121627, 2017). "UA also suppressed colon cancer cell migration by inhibiting MMP9 and upregulating CDH1 expression." (PMID 23737956, 2013). "The results showed the anti-proliferation, anti-migration and pro-apoptotic effects of UA in colon cancer cells were mediated through simultaneous modulation of multiple signaling pathways, including MMP9/CDH1, Akt/ERK, COX-2/PGE2, p300/NF-κB/CREB2 and cytochrome c/caspase-dependent pathways." (PMID 23737956, 2013). "This unattached phenotype suggests a defect in cell adhesion, and in the panel of colon cancer lines only NCI-H716 and RKO cells lacked both EPCAM and CDH1 expression." (PMID 24968263, 2014).
pancreatic cancer (417 papers, 2002 to 2026). "In research on pancreatic cancer, the genetic inactivation of E-cadherin (encoded by the CDH1 gene) was found to induce EMT and promote metastasis in vivo." (PMID 40260239, 2025). "Additionaly, an E-cadherin (CDH1) mutation with high variant allele frequency was identified in both pancreatic tumor tissue and plasma." (PMID 40236650, 2025). "A recent report also described a relationship between CDH1 germline mutations and colorectal signet-ring cell cancer; however, the development of pancreatic cancer has been rarely documented." (PMID 40236650, 2025). "It was reported that the overexpression of BACH1 induced by tank binding kinase 1 (TBK1) increases intracellular labile iron and decreases the expression of E-cadherin (encoded by CDH1), thereby promoting the metastasis of pancreatic cancer cells." (PMID 38321558, 2024). "Most sites from which tumors are most likely to metastasize—colorectal, esophageal, lung, ovarian, and pancreatic cancer—had low prevalences of both CDH1 and CTNNB1 mutations." (PMID 29156750, 2017). "In 25 human pancreatic cancer resection specimens, the coding region of the E-cadherin gene (CDH1) was sequenced for somatic mutations." (PMID 24084722, 2013). "Moreover, expression of CDH1, encoding E-cadherin, is downregulated in pancreatic cancer cells by binding of repressor complexes comprised of HDACs and certain transcription factors such as ZEB1 or Snail." (PMID 36497404, 2022). "In a pancreatic cancer mouse model, adenomas convert to carcinomas with the loss of CDH1." (PMID 23110125, 2012). "The metastasis of pancreatic cancer is associated with colon cancer protein 1 (MACC1), which positively interacts with SNAI1; this interaction represses CDH1 (which encodes E-cadherin) and enhances fibronectin 1 (FN1) expression, which promotes cell migration." (PMID 39941895, 2025). "To further validate the correlations found, we analyzed publicly available datasets using TNMplot and observed significant correlations between AQP3 and c-Jun (p < 0.01), and AQP5 with EGFR (p = 0.040) and CDH1 (p < 0.01) in pancreatic cancer." (PMID 40305202, 2025). "In pancreatic tumor tissues, CDH1 was correlated with EGFR (r = 0.744, p < 0.05) and ERK1 (r = 0.689, p < 0.05)." (PMID 40305202, 2025). "Initially, we determined the epithelial and/or mesenchymal states of the pancreatic cancer cell lines by assessing the expression of two extensively used markers, CDH1 and VIM, by ICC." (PMID 40531655, 2025). "Transcript expression levels of CDH1 and VIM were also analyzed according to the aggressiveness and invasiveness grade of tumors to ascertain associations with such pancreatic cancer features." (PMID 40305202, 2025). "Zinc finger E-box-binding homeobox 1, a TF, recruited HDAC complexes to CDH1 promoter sequences to decrease the expression of CDH1 in pancreatic cancer (PC) cells." (PMID 36968022, 2023). "HDAC1 is recruited to the CDH1 promoter in pancreatic cancer cells, resulting in deacetylation of histone 3 and 4 proteins in the nucleus and E-cadherin depletion, which aids in the epithelial-mesenchymal transition (EMT)." (PMID 36034650, 2022). "The recruitment of HDAC1 and HDAC2 by the transcriptional repressor ZEB1 results in CDH1 down regulation in pancreatic cancer." (PMID 35144601, 2022). "Snail mediates the recruitment of the Sin3A/HDAC1/2 complex into the CDH1 promoter, where it inhibits CDH1 expression and enhances pancreatic cancer metastasis." (PMID 35144601, 2022). "In pancreatic cancer, the Snail/HDAC1/2 complex was shown to repress CDH1, causing a reduction in E-cadherin expression and subsequently inducing EMT." (PMID 34395273, 2021). "RING1A/1B was reported to interact with SNAI1, another EMT-TF, and contribute to SNAI1-mediated repression of CDH1 in pancreatic cancer cells." (PMID 33779563, 2021).
pancreatic cancer (continued). "ZEB1 is a repressor of the CDH1 gene in pancreatic cancer, and the CDH1 gene is epigenetically silenced during the dynamic EMT process." (PMID 34881179, 2021). "E-cadherin, encoded by the CDH1 gene, is a key player against EMT (epithelial-to-mesenchymal transition), and it appeared to also be epigenetically regulated in pancreatic cancer." (PMID 32183227, 2020). "Assessment of CDH1 together 11 genes in 15 types of cancer including pancreas cancer was corresponded to effect on several biological processes such as apoptosis, cell cycle regulation." (PMID 29511477, 2017). "Dysfunction of the CDH1-mediated cell adhesion system plays an important role in pancreatic tumor progression to invasive, metastatic carcinoma." (PMID 26918727, 2016). "Our studies provide convincing evidence that nuclear HDAC3 and cytoplasmic CDH1 have independent prognostic value in pancreatic cancer and provide novel targets for prognostic therapeutics." (PMID 26918727, 2016). "E-cadherin (CDH1 gene) is suppressed in several cancer types including pancreatic cancer by its repressors ZEB1 (zinc finger E-box-binding homeobox 1) and SIP1 (Smad-interacting protein 1, ZEB2, and SMADIP1) which thus act as EMT-activators." (PMID 25960741, 2015). "Although aberrant methylation is a frequent epigenetic event for a number of genes in pancreatic cancer, in the present study, promoter methylation was present in only 4 of 9 investigated genes and only resulted in reduced mRNA expression one of them, CDH1." (PMID 23718921, 2013). "Previously, we have shown that the gene expression of MBD1 is significantly increased in pancreatic carcinomas compared to normal pancreatic tissue, with a simultaneous decrease in the expression of some tumor suppressor genes (CDH1, RB)." (PMID 18445260, 2008). "It has also been reported that RA induces upregulation of CDH1 expression and the morphological change of fibroblastoid to epithelioid growth of human pancreatic cancer cell line SUIT-2." (PMID 14970867, 2004). "Contrary to expected, AQP5 was positively correlated with CDH1 in pancreatic tumor tissues." (PMID 40305202, 2025). "Among the previously known and here confirmed interactors (CDH1, DISP1, SCFD1, USE1, TSG101, and USP8), CDH1 (E‐cadherin), a critical adhesion molecule, is frequently lost or downregulated in pancreatic cancer, promoting epithelial‐to‐mesenchymal transition (EMT) and enhancing tumor invasiveness." (PMID 40952239, 2025). "CDH1 and VIM transcript expression were analyzed by qPCR, according to different variables to ascertain associations with patients’ specific features and predisposition to develop pancreatic cancer." (PMID 40305202, 2025). "Similarly, it has been recently reported that pancreatic carcinomas retain CDH1 expression, despite exhibiting high invasiveness and metastatic potential." (PMID 40710723, 2025). "Moreover, Zeb1 was also found to form a repressor complex with Sirt-1 (a class-III histone deacetylase (HDAC)), which binds the promoter region of CDH1 and suppresses its expression in prostate and pancreatic cancer cells undergoing EMT." (PMID 34708244, 2022). "In this study, we investigated the synergistic effects of juglone and selenium on PANC-1 and BxPC-3 pancreatic cancer cell lines by cell adhesion and invasion assays and evaluation of the mRNA and protein expressions of CDH1, ITGB3 and COL4A3 which play role in metastasis and angiogenesis processes." (PMID 36407358, 2022). "In pancreatic cancer, effective immunotherapy is likely to require upregulation of CDH1 expression." (PMID 36315446, 2022).
pancreatic cancer (continued). "Importantly, it has been shown that a decrease of CDH1 expression can solely be responsible for pancreatic cancer metastasis." (PMID 32414223, 2020). "Taken together, these results indicate that LINC00261 might be involved in the regulation of CDH1 transcription, thereby controlling the epithelial identity of pancreatic cancer cells." (PMID 32414223, 2020). "Furthermore, knockdown MAP4K5 in pancreatic cancer cell lines led to decreased CDH1 mRNA expression." (PMID 27023625, 2016). "However, only miR-103 was directly involved in the regulation of pancreatic cancer-associated processes: E-cadherin signalling events (CDH1), TGF beta signalling pathway (TGFBR2, APC, CDH1, CREBBP, EP300, SMAD3, TSC2), and altered TFG-beta SMAD dependent signalling (TGFBR2, SMAD3, and FBXW7)." (PMID 29285254, 2017). "The knockdown of MAP4K5 in pancreatic cancer cell lines leads to decreased CDH1 mRNA expression, highlighting the essential role of MAP4K5 in regulating E-cadherin expression and EMT59." (PMID 41034525, 2025). "In the present study, the gene expression of key players in EMT—CDH1 and VIM—and the MAPK/ERK pathway—EGFR, ERK1, ERK2, c-Jun, and c-Fos—was assessed in paired healthy and neoplastic tissues of the same pancreatic cancer cohort." (PMID 40305202, 2025). "In the present study, we evaluated the expression of CDH1, VIM, EGFR, ERK1, ERK2, c-Jun, and c-Fos in 24 paired healthy and tumor tissues from pancreatic cancer patients who underwent resection surgery." (PMID 40305202, 2025). "For instance, in pancreatic tumors, the expression of SOX9 positively correlates with the expression of epithelial phenotype genes (CDH1, KRT7, KRT18, and KRT19) and negatively correlates with the expression of the mesenchymal phenotype gene VIM." (PMID 35884771, 2022). "Our review of recent pancreatic cancer studies has revealed a focus on CDH1 and CCDC80 as genes that suppress EMT markers or impact EMT processes in pancreatic cancer progression." (PMID 33928036, 2021). "In pancreatic cancer cells, HDAC1 is recruited to the CDH1 promoter, resulting in deacetylation of histone 3 and histone 4 proteins in the nucleus and depletion in E-cadherin, which consequently helps in the epithelial–mesenchymal transition (EMT)." (PMID 32210140, 2020). "In pancreatic cancer, downregulation of E-cadherin occurs through ZEB1, which recruits HDAC1 and HDAC2 to the CDH1 promoter to silence its expression." (PMID 26905733, 2016). "In vitro cultured ovarian and pancreatic cancer cells showed upregulation of SNAIL2 and downregulation of CDH1 upon BMP4 incubation." (PMID 27191723, 2016). "Here, we investigate the prognostic significance of aberrant CDH1 and HDAC3 localization in 84 pancreatic cancer patients." (PMID 26918727, 2016). "Moreover, LOXL2 promotes the activation of FAK/SRC and is involved in regulation of expression of CDH1, Snail, and L1CAM, all of which are related to EMT and invasiveness of pancreatic tumor cells." (PMID 38560567, 2024). "In pancreatic cancer cells, ILF2 overexpression increases migration and invasion by regulating genes involved in epithelial-mesenchymal transition, such as upregulating vimentin (VIM) and fibronectin 1 (FN1) while downregulating cadherin 1 (CDH1/E-cadherin)." (PMID 39735599, 2024). "In this report, we discovered that KDM2B, a member of variant PRC1 complex and also a histone H3 demethylase, epigenetically regulated the downregulation of several epithelial marker genes including CDH1, which was indispensable for TGF-β-induced EMT of lung and pancreatic cancer cells." (PMID 33779563, 2021). "In pancreatic cancer cells, the transcription factor ZEB1 plays a key role inthe regulation of EMT and the metastatic process by suppressing the E-cadherinexpression via the recruitment of HDAC1 and HDAC2 deacetylases to the promoterregion of the CDH1 gene." (PMID 33173593, 2020).
pancreatic cancer (continued). "Moreover, LOXL2 contributes positively to the activation of FAK/SRC and influences the expressions of CDH1, Snail and L1CAM, which are all related to EMT and the invasiveness of pancreatic tumor cells." (PMID 27285767, 2016). "As expected, epithelial markers (Krt7, Krt8, Krt18, Krt19, Epcam, Egfr, Cdh1) were highly expressed in primary pancreatic tumors and in the cancer cell line NB508 and nearly absent in the nonepithelial MEFs and in normal WBCs." (PMID 25242334, 2014). "Recruitment of HDACs to the CDH1 promoter is regulated by the transcription factor ZEB1, and inhibition of HDACs may be a promising antitumour therapy for pancreatic cancer." (PMID 24084722, 2013). "Finally, SPINT1 knockdown in the pancreatic cancer cell line SUIT-2, induced EMT and invasion which were accompanied by ZEB2 elevation and CDH1 reduction." (PMID 21747944, 2011). "Furthermore, dual cadherin antibodies recognizing CDH1 (epithelial E‐cadherin) and CDH11 (mesenchymal OB‐cadherin) have been reported to target circulating tumor cells and inhibit bloodborne metastasis in breast and pancreatic cancers." (PMID 41263259, 2025).
melanoma (385 papers, 2004 to 2026). A malignant, usually aggressive tumor composed of atypical, neoplastic melanocytes. "CDH1 is a known invasion-suppressor gene, and its loss or abnormal expression can increase the migration capabilities of melanoma cells." (PMID 40954493, 2025). "To induce melanoma, we combined Cdh1 loss with the NRAS(Q61K) mutation using the Tyr::NRASQ61K/°; Cdkn2a+/− model." (PMID 40500450, 2025). "Of these, only CDH1 mRNA levels were lower in young women than in men or older women, indicating that reduced CDH1 expression could increase oestrogen-driven cancer susceptibility, particularly in melanoma." (PMID 40500450, 2025). "Cdh1 loss is often linked to enhanced β-catenin signalling, reflected here by increased promoter activation of β-catenin targets such as Apcdd1, Axin2, Nkd1, Notum and Sp5—primarily in ∆Ecad female melanomas—with corresponding gene expression." (PMID 40500450, 2025). "Interestingly, transgenic expression of CDH1 in melanoma blocks p38 signaling, suggesting that the loss of CDH1 leads to a more active p38 pathway indicating a direct crosstalk between p38 activity and CDH1 expression." (PMID 33172202, 2020). "Of note, we detected a strong downregulation of the CDH1 gene in the primary melanoma cells, whilst it came back in the metastatic cells." (PMID 40332096, 2025). "At the validation level of gene expression (TCGA-SKCM), except for CDH1, all the hub genes were downregulated in metastasis as compared to primary melanoma tumors." (PMID 40722520, 2025). "To investigate the role of E-cadherin in female-biased melanoma, we developed a melanoma mouse model with conditional Cdh1 deletion in melanocytes (Tyr::CreA/°; Cdh1F/F)." (PMID 40500450, 2025). "Upregulation of CDH1 in both melanoma phenotypes following corin treatment also suggests corin-associated inhibition of an EMT-like phenotype switch in these cells." (PMID 38300709, 2024). "In fact, A375P melanoma cells up-regulated the expression of CDH1 while down-modulated CDH2 after exposure to hEo33-EV or co-culture with hEo33." (PMID 39061080, 2024). "The EZH2-mediated elevation of H3K27me3 has been described to be involved in epigenetic silencing of the tumor suppressor genes RUNX3 and CDH1 in advanced-stage human melanoma tissues." (PMID 35163453, 2022). "SIRT1 induces epithelial-mesenchymal transition (EMT) in melanoma cells by down-regulating E-cadherin (CDH1) and up-regulating N-cadherin (CDH2) and vimentin (VIM)." (PMID 36139919, 2022). "We found that Cav1 and E-cadherin (CDH1) were upregulated in de-differentiated or differentiated melanomas, respectively." (PMID 36271142, 2022). "Variants highly associated with melanoma were also found in three other regions: oculocutaneous albinism 2 (OCA2, chr15:27670078–28337214), E-cadherin (CDH1, chr16:68528729–68923897) and cyclin D1 (CCND1, chr11:69210414–69803433)." (PMID 35357426, 2022). "Based on ourresults, enhancement of SOX2 at the mRNA and protein level in tumor tissuesas well as melanospheres, can enhance the expression of miR-9, which results in an increasedmotility of melanoma cells through reduction of CDH1 level." (PMID 34308569, 2021). "Further evidence in human melanoma cells suggests that GLI2 is directly responsible for turning off the E-cadherin gene (CDH1) expression during EMT in addition to enhancing the transcription of other EMT activators." (PMID 33494284, 2021). "The activity of genes encoding E- and N-cadherins (CDH1, CDH2) was detected in melanoma cells prepared from the spheroids." (PMID 33182777, 2020).